H19 (H19 imprinted maternally expressed transcript)
Diseases named in the same sentence as H19 in open-access papers (continued):
Sharing a sentence is not in itself a finding about the gene and the disease.
prostate carcinoma (60 papers, 2013 to 2026). A carcinoma that arises from epithelial cells of the prostate gland. "Studies have corroborated the functions of H19 single-nucleotide polymorphisms (SNPs) in prostate cancer by affecting perineural invasion of this cancer." (PMID 37253635, 2023). "Two additional SNPs in H19, rs3024270 or rs3741219, were shown to be associated with the risk of perineural invasion of prostate cancer." (PMID 34946977, 2021). "Based upon our proposed method, prostate cancer was predicted to be associated with H19, MALAT1, CDKN2B-AS1, HOTAIR, PCAT1, SRA1, XIST." (PMID 29671405, 2018). "PIM1 was also showed to promote highly aggressive, neuroendocrine variant of prostate cancer by epigenetic changes in H19, suggesting it may be implicated in malignant neuroendocrine transformation." (PMID 32504181, 2020). "The present study assessed how H19 polymorphisms interplay with the clinicopathologic characteristics of prostate cancer, especially in patients with relatively low iPSA levels (low risk of prostate cancer) to identify the best candidates for curative treatments." (PMID 32878251, 2020). "However, limited data on the associations between H19 SNPs and prostate cancer are available." (PMID 32878251, 2020). "High H19 expression has been shown to be a contributor to several human cancers, including bladder, colorectal, and prostate cancers." (PMID 40452889, 2025). "Taken together, our findings expand the biological role of BRD4 in prostate cancer metastasis and introduce a novel regulatory axis involving H19 as a critical modulator of adhesion gene transcription." (PMID 40407591, 2025). "This is the first study demonstrating that BRD4 promotes the collective migration phenotype in prostate cancer through a mechanism dependent on H19." (PMID 40407591, 2025). "Overall, this study highlights the critical role of the circuitry of H19/cell adhesion molecules in prostate cancer progression." (PMID 39457633, 2024). "Our study demonstrated that lncRNA H19 exhibited a higher level in prostate cancer tissues compared to adjacent normal tissues." (PMID 37253635, 2023). "To conclude, Brevilin A modulates the biological behaviors of prostate cancer cells via the lncRNA H19/miR-194/E2F3 axis." (PMID 37253635, 2023). "In conclusion, our study has confirmed that Brevilin A impedes prostate cancer cell proliferation, migration, and invasion and exerts its anti-tumor function in prostate cancer through modulating the lncRNA H19/miR-194/E2F3 signaling pathway." (PMID 37253635, 2023). "CCK8 assay displayed that in contrast with the H19 group, Brevilin A impeded prostate cancer cell viability." (PMID 37253635, 2023). "All discoveries unveiled that lncRNA H19 restrained miR-194 expression to bolster prostate cancer cell proliferation and migration." (PMID 37253635, 2023). "Transwell assay denoted that by contrast to the H19 group, Brevilin A dampened prostate cancer cell migration and invasion." (PMID 37253635, 2023). "A xenograft model of prostate cancer nude mice was taken to confirm the impact of Brevilin A and lncRNA H19 on cancer cell growth." (PMID 37253635, 2023). "For example, it was reported that the expression level of lncRNA H19 was significantly downregulated in the metastatic prostate cancer cell line and negatively correlated with the expression of the extracellular matrix protein TGFBI." (PMID 37552338, 2023). "To dig into the functions and mechanisms of Brevilin A in vivo, we established a nude mouse xenograft model of prostate cancer using DU145 cells stably transfected with lncRNA H19 overexpression plasmids and adopted Brevilin A for treatment." (PMID 37253635, 2023). "Our study probed the functions of Brevilin A in prostate cancer cells and the mechanisms among Brevilin A, lncRNA H19, miR-194, and E2F3 on the biological behaviors of the cells." (PMID 37253635, 2023).
prostate carcinoma (continued). "Pyrosequencing analysis of DMRs in corresponding prostate and prostate cancer tissue samples revealed frequent hypo- and hypermethylation at the H19/IGF2:IG DMR in both benign and cancerous tissues." (PMID 35804856, 2022). "H19 is found to be downregulated together with miR675 in prostate cancer and takes part in biological processes through miRNA’s combination with its downstream." (PMID 34162418, 2021). "Increased expression of H19 was observed in prostate cancer patients with a high Gleason score compared to a low Gleason score and benign prostatic hyperplasia (BPH)." (PMID 34946977, 2021). "Although evidence suggests that H19 functions as an oncogene, its expression and regulatory mechanism in prostate cancer remain controversial." (PMID 32878251, 2020). "Further large-scale studies are warranted to examine the roles of regulatory lncRNA H19 in prostate cancer." (PMID 32878251, 2020). "In conclusion, our results suggested that H19 SNPs play a role in the perineural invasion of prostate cancer." (PMID 32878251, 2020). "Regarding the specific function of H19 in prostate cancer, an inhibitory role in cell migration for the H19 internal microRNA, miR-675, has been identified in metastatic prostate cancer cell line by Zhu and colleagues." (PMID 31426484, 2019). "We found that H19 is significantly induced by hypoxia and by estrogens in hormone-driven tumor cells, such as breast and prostate cancer cells." (PMID 31426484, 2019). "Under combined treatment, we observed, at least in aggressive prostate cancer, a specific inhibition of H19 expression that leads to the release of cell adhesion molecules transcription." (PMID 31426484, 2019). "The axis of lncRNA H19-miR-675-TGFBI had possible diagnostic and therapeutic potential for advanced prostate cancer." (PMID 30103699, 2018). "A decrease in the expression of the pluripotency transcription factors Oct4 and Sox2 was also observed in human prostate cancer cells following knockdown of H19." (PMID 26415227, 2015). "Altogether, these results indicate a suppressor role for the H19/miR-675 axis in prostate cancer metastasis." (PMID 26110379, 2015). "Interestingly, H19 has also been reported to exert tumor-suppressive effects in several cancer types, including liver cancer 45, retinoblastoma 46, and prostate cancer." (PMID 41208889, 2025). "Besides HDACs, GSK-J4, a histone lysine demethylase inhibitor, was demonstrated to interrupt an H19/cell adhesion molecules circuitry relevant to prostate cancer metastasis." (PMID 40885718, 2025). "It regulates prostate cancer cells through the lncRNA H19/miR-194/E2F3 axis." (PMID 41157091, 2025). "Consequently, Brevilin A dampened prostate cancer cell proliferation, migration, and invasion, suppressed the expressions of lncRNA H19 and E2F3, and enhanced miR-194 level." (PMID 37253635, 2023). "Our experiments denoted that Brevilin A could frustrate prostate cancer cell proliferation, migration, and invasion, repress lncRNA H19 expression, and invert the pro-cancer function of lncRNA H19." (PMID 37253635, 2023). "There is a positive relationship between H19 and miRNA-675 in prostate cancer." (PMID 35773731, 2022). "LncRNA H19-mir675 axis may inhibit the metastasis of prostate cancer by transforming growth factor beta induced protein (TGFBI)." (PMID 36406273, 2022). "The function of H19 remains controversial in multiple cancers, including prostate cancer." (PMID 34946977, 2021). "Studies have indicated that H19 might act as an oncogene in prostate cancer by the upregulation of SRY box 2 (SOX2) and POU domain class 5 transcription factor 1 (POU5F1)." (PMID 32878251, 2020). "H19 is overexpressed in both leukemia and different types of solid cancers including glioma, melanoma, lung adenocarcinoma, breast, ovarian, and prostate cancers, as well as cancers of digestive (tongue, stomach, colon, liver, pancreas) and urinary systems (kidney, bladder)." (PMID 33291403, 2020).
prostate carcinoma (continued). "However, the data are limited for connections between H19 SNPs and prostate cancer, especially regarding variations at rs3024270 and rs3741219." (PMID 32878251, 2020). "H19 single-nucleotide polymorphisms (SNPs) have been found to play crucial roles in numerous malignancies, but not yet in prostate cancer." (PMID 32878251, 2020). "For instance, lncRNA H19 is downregulated in the prostate cancer cell line M12, and the overexpression of H19 suppresses cell migration in prostate cancer cell lines, which suggests H19 may play a suppressive role in prostate cancer progression." (PMID 33013201, 2020). "Here, we focused our attention on the role of H19 in the molecular mechanisms by which estrogen and hypoxia signaling might favor the acquisition of an aggressive phenotype in prostate cancer." (PMID 31426484, 2019). "Our data suggest that H19 may exert a different function in prostate cancer depending on tumor properties and tumor microenvironment." (PMID 31426484, 2019). "However, a single lncRNA can regulate multiple target genes, for example, H19 targets TGFβ1 in prostate cancer cells, and TGFβ1 is a key regulator in CCA inflammation, suggesting the pivotal role of inflammation regulation by special lncRNAs." (PMID 30305026, 2018). "In prostate cancer cells, H19 is upregulated that aids in expression of miR-675." (PMID 29579063, 2018). "H19 may be one of the earliest identified cancer lncRNAs, the up-regulation of H19 could repress cell migration of prostate cancer." (PMID 27580177, 2016). "H19/miR-675 axis inhibits prostate cancer metastasis via affecting TGFBI expression." (PMID 27391349, 2016). "Represses prostate cancer metastasis through TGFβ1 via H19/miR-675." (PMID 26110379, 2015). "The role of H19 in prostate carcinogenesis and tumour growth has yet to be fully elucidated and, as with the miRNAs, it has been described as both an oncogene and tumour suppressor depending on the context, although it’s up-regulation is correlated with increased metastasis in prostate cancer." (PMID 35205253, 2022). "Furthermore, H19/miR-675 repressed prostate cancer metastasis by targeting TGFBI." (PMID 35674441, 2022). "These limitations might underestimate the risks of H19 SNPs in prostate cancer prognosis." (PMID 32878251, 2020). "Our study provides novel insight into the epigenetic regulation of metastatic dissemination in prostate cancer (PCa), identifying the BET family protein BRD4 as a key driver of the H19/cell adhesion molecule axis that promotes collective cell migration." (PMID 40407591, 2025). "In conclusion, our study identifies a novel and clinically relevant regulatory axis in metastatic prostate cancer, wherein BET family proteins—particularly BRD4—function as central epigenetic effectors of the H19/cell adhesion molecule circuitry." (PMID 40407591, 2025). "In-vitro assays also denoted that lncRNA H19 overexpression could facilitate PCa cell proliferation, invasion, and migration and suppress apoptosis, whereas lncRNA H19 down-expression could produce the opposite phenomenon, showing that lncRNA H19 could exert a promotive function in prostate cancer." (PMID 37253635, 2023). "qRT-PCR suggested that lncRNA H19 and E2F3 expressions were obviously elevated in prostate cancer tissues versus adjacent normal tissues, while miR-194 expression was substantially lowered." (PMID 37253635, 2023). "By promoting miRNA-675 expression, H19 reduces TGF-β levels, leading to metastasis suppression of prostate cancer cells." (PMID 35773731, 2022). "In this study, we examined the in vitro effects of altering metabolic conditions on IGF-II imprinting status, IGF-II / H19 mRNA, and IGF-II peptide levels in the PC3 prostate cancer cell line." (PMID 33669311, 2021). "In prostate CSCs, H19 expression has been shown to promote both resistance to the androgen deprivation therapy (ADT) and the induction of highly metastatic form of prostate cancer." (PMID 33291403, 2020).
prostate carcinoma (continued). "Identical results were found in prostate cancer (PCa) cell lines where PIM kinases drive cancer growth, and both H19 and stem cell gene levels." (PMID 32146726, 2020). "All findings confirmed that the aberrant profiles of lncRNA H19, miR-194, and E2F3 might be correlated with prostate cancer." (PMID 37253635, 2023). "LncRNA H19 and E2F3 were uplifted, whereas miR-194 was abated in prostate cancer cells and tissues." (PMID 37253635, 2023). "Additionally, lncRNA H19 and E2F3 were more highly expressed in prostate cancer cell lines than in human prostate epithelial cells PrEC, whereas miR-194 expression exhibited the opposite result." (PMID 37253635, 2023). "It has been found that lncRNA H19 and its derived miR-675 are downregulated in metastatic compared to non-metastatic prostate cancer cell lines, while H19 upregulation increased miR-675 levels and inhibits metastatic cells migration." (PMID 37464436, 2023). "Through the establishment of a prostate cancer nude mouse model, we discovered that lncRNA H19 bolstered tumor growth, augmented positive Ki67 cells, and enhanced E2F3 expression, whereas Brevilin A dampened the promoting effect of lncRNA H19." (PMID 37253635, 2023). "Long non-coding RNA H19 and H19-derived microRNA-675(miR-675) were significantly down-regulated in the metastatic prostate cancer cell line M12 compared with the non-meta-static prostate epithelial cell line P69." (PMID 31760932, 2019). "In contrast, the methylation of IGF2/H19-ICR (imprinting control region with a CTCF binding site located between IGF2 and H19 genes) was not significantly different between the prostate cancer groups TUR-BPH, RP-BPH and RP-PCa." (PMID 29017567, 2017). "Meanwhile, H19 could serve as precursor of the tumor suppressor gene microRNA-675, attenuating cancer cell motility through the downregulation of TGF-β1 in prostate cancer." (PMID 27806310, 2016). "Overexpression of PLAGL1 induced IGF2, H19, and CDKN1C expression in a prostate cancer cell line." (PMID 26115033, 2016). "H19 and its derivative miR-675 were both significantly down-regulated in metastatic prostate cancer cells but not in non-metastatic prostate cancer cells." (PMID 26110379, 2015). "Our research intended to probe the regulatory relationship among Brevilin A, lncRNA H19, miR-194, and E2F3 and their influence on the biological behaviors of prostate cancer cells, and the mechanism of Brevilin A affecting lncRNA H19 expression in prostate cancer was investigated." (PMID 37253635, 2023). "Consequent expression analyses in the prostate cancer tissues showed a significantly diminished expression of the imprinted genes PLAGL1/ZAC1 (OMIM 603044), MEG3 (OMIM 605636), NDN (OMIM 602117), CDKN1C, IGF2, and H19, whereas KCNQ1OT1 was significantly overexpressed." (PMID 35804856, 2022). "H19 is a significantly down-regulated lncRNA in prostate cancer confirmed to inhibit the invasion of tumor cells by targeting TGFBI via regulating miR-675, which could be a biomarker to benefit diagnosis and therapy of advanced prostate cancer." (PMID 35087800, 2021). "In addition, a comparative clinical cohort of prostate cancer tissue was analysed for expression of IGF-II and H19 mRNA using digital droplet polymerase chain reaction (ddPCR) and compared with two larger publicly available patient cohorts from the Cancer Genome Atlas (TGCA)." (PMID 33669311, 2021). "After quantifying IGF-II and H19 mRNA expression in the PrEvENT cohort, we utilised the cBioPortal for Cancer Genomics website to assess whether co-expression of IGF-II and H19 mRNA existed, in a larger prostate cancer cohort, as well as another hormone-responsive cancer type: breast." (PMID 33669311, 2021).
liver cancer (56 papers, 2013 to 2025). An epithelial or non-epithelial malignant neoplasm that arises from the liver. "m5C on H19 increases transcript stability and promotes the recruitment of the oncoprotein G3BP1, supporting proliferation and tumor progression; higher H19 m5C and expression levels are associated with poor differentiation in patients with liver cancer." (PMID 41301491, 2025). "LncRNA H19 can regulate microRNA-22 expression in HBV-associated liver cancer, which is closely related to tumor proliferation, invasion and metastasis." (PMID 34869051, 2021). "H19 polymorphisms have been proven to regulate the methylation of the MDR1 promoter in liver cancer cells, resulting in chemotherapy resistance." (PMID 34199840, 2021). "Since H19 gene polymorphisms were found to be correlated with susceptibility to liver cancer, the relationship between the H19 gene variations and clinicopathologic characteristics of HCC patients was also evaluated in this study." (PMID 31277475, 2019). "In this study, we found that two exonic SNPs of H19, rs2839698 and rs3741219, are correlated with elevated susceptibility to liver cancer." (PMID 31277475, 2019). "In conclusion, our results indicate an association between H19 gene polymorphisms and the incidence and progression of liver cancer." (PMID 31277475, 2019). "H19 ncRNA expression was shown to result in high H19 protein expression in liver cancer whenever there is a loss of imprinting." (PMID 29671405, 2018). "H19 is highly expressed in proliferative tissues, including liver regenerating after injury, and its first exon encodes miR-675, whose overexpression promotes liver cancer." (PMID 32428001, 2020). "Given that females have a lower risk of developing liver cancer and that in this study, H19 had a higher expression in females, H19 could potentially suppress hepatic tumors in females." (PMID 29846646, 2018). "To identify whether miR675 oncogenic activity was caused by H19, we further determine the H19 function in liver cancer cells." (PMID 26376677, 2015). "Growing evidence confirms that lncRNA H19, an endogenous noncoding single-stranded RNA, acts as an oncogene in the genesis and progression of liver cancer." (PMID 39697114, 2025). "For instance, exosomes from CD90 + liver cancer cells contain lncRNA H19, which can be internalized by endothelial cells, promoting an angiogenic phenotype and enhancing intercellular adhesion." (PMID 40781643, 2025). "m5C-modified H19 promotes liver cancer development by recruiting Ras-GTPase-activating protein SH3 domain-binding protein 1 (G3BP1)." (PMID 40370440, 2025). "CSC-like CD90+ liver cancer cells released lncRNA H19, which modulated endothelial cells to promote angiogenesis and tumor cell adhesion to the endothelial cell monolayer." (PMID 39676873, 2024). "H19 is involved in a variety of cancer hallmarks, including the pro-oncogenic inflammatory environment that characterizes liver cancer." (PMID 38095719, 2024). "Studies have shown that H19 plays a key role in multiple drug resistance, especially in liver cancer, breast cancer, and colorectal cancer." (PMID 36960964, 2023). "This review will summarize the current understanding of lncRNAs and H19 in hepatic cancer development." (PMID 36960964, 2023). "Meanwhile, lncRNA-H19 is enriched in CD90+ liver cancer cells, and antisense H19 oligonucleotide transfection induces a remarkable increase in the ratio of MDR1 promoter methylation, which gives rise to doxorubicin accumulation." (PMID 35945536, 2022). "The four lncRNAs HOTAIR1, MALAT1, MEG3 and H19 have been proved to be highly correlated with primary liver cancer." (PMID 34633988, 2021). "The role of H19 in liver cancer was intensely investigated, but the reported findings are conflicting." (PMID 33499244, 2021). "To understand the contribution of H19 to liver cancer development, we investigated miR-675, which is generated from the first exon of the H19 RNA message." (PMID 33499244, 2021).